C19orf18 (chromosome 19 open reading frame 18)
Synonyms: MGC41906
Tractability: Antibody: UniProt predicts a signal peptide or a membrane-spanning region.
Gene: Protein-coding gene on chromosome 19 (57,958,437 to 57,974,534, reverse strand). Ensembl gene ENSG00000177025.
Subcellular location: Membrane
Subcellular location (Human Protein Atlas): Golgi apparatus
Gene Ontology:
Molecular function: protein binding
Cellular component: extracellular exosome; membrane
Genetic constraint (gnomAD): Loss-of-function variants: 15 observed, 20.08 expected, observed/expected ratio (o/e) 0.75, 90% interval 0.5 to 1.15. The upper end of that interval is the gene's LOEUF score, 1.15, which puts it in group 5 of 6, group 1 being the genes least tolerant of losing a copy. Missense variants: 172 observed, 179.95 expected, observed/expected ratio (o/e) 0.96, 90% interval 0.84 to 1.09. Synonymous variants: 71 observed, 70.31 expected, observed/expected ratio (o/e) 1.01, 90% interval 0.83 to 1.23.
Homologues: Orthologues: chimpanzee C19H19orf18 (99% identical), rabbit C19orf18 (52% identical), rat C1h19orf18 (41% identical), mouse 2900092C05Rik (40% identical).